ALB (albumin)
Diseases named in the same sentence as ALB in open-access papers (continued):
Sharing a sentence is not in itself a finding about the gene and the disease.
Sepsis (continued). "Overall, the findings underscore the intricate relationship between inflammatory markers like sPLA2, albumin structure and function, and nutritional strategies in the management of sepsis, highlighting the potential benefits of tailored feeding approaches." (PMID 39273360, 2024). "The dual serum assays for sPLA2 and albumin were capable of assessing and evaluating the benefits of permissive feeding compared with standard feeding in patients with sepsis." (PMID 39273360, 2024). "Recently, researchers have extensively explored indicators for predicting prognosis in sepsis patients, including lactate/albumin ratio, glucose/lymphocyte ratio, neutrophil/lymphocyte ratio, and platelet/lymphocyte ratio." (PMID 39193015, 2024). "In adults with sepsis or septic shock, albumin is suggested to be joined when extensive volumes of crystalloids are used—weak recommendation but moderate quality of evidence." (PMID 38254870, 2024). "Although the role of serum albumin level in the prediction of sepsis severity has been investigated in different regions of the world, in Pakistan, research work on the correlation between serum albumin level and severity of sepsis is limited." (PMID 39539863, 2024). "First, severe oxidative stress and capillary leak have been correlated with lower serum albumin levels in sepsis." (PMID 38826606, 2024). "It is being postulated that CRP and serum albumin are useful markers that can predict mortality in patients with sepsis." (PMID 39252713, 2024). "Albumin replacement did not improve survival at 28 and 90 days in patients with severe sepsis and septic shock in the Albumin Italian Outcome Sepsis trial." (PMID 38378647, 2024). "Serum albumin level is a readily available, inexpensive, and easily interpretable biomarker that can facilitate early identification of sepsis severity." (PMID 39539863, 2024). "Several studies have validated the clinical significance of the blood urea nitrogen to albumin ratio (BAR) in predicting the prognosis of sepsis, severe pneumonia, and other diseases." (PMID 39013924, 2024). "Recently, many studies have proposed new composite indices to predict the inpatient mortality rate of sepsis patients, such as the lactate/albumin ratio, glucose/lymphocyte ratio, neutrophil/lymphocyte ratio, and platelet/lymphocyte ratio." (PMID 39193015, 2024). "The results showed that increased serum sPLA2 activity was correlated with decreased albumin FA/lipid binding capacity during sepsis." (PMID 39273360, 2024). "Further multivariable analysis suggested that the mortality of sepsis-induced ARDS patients admitted to ICU was associated with APACHE II score, Mrp 8/14 and albumin levels." (PMID 39686985, 2024). "In our study, we observed that patients with sepsis exhibited higher serum albumin and platelet levels than those with septic shock." (PMID 38576552, 2024). "In SSCG 2021, “for adults with sepsis or septic shock, albumin use in patients who received large volumes of crystalloids over using crystalloids alone is suggested (Weak recommendation, low quality of evidence, Recommendation 34)”." (PMID 38658435, 2024). "Patients with sepsis with low albumin levels and high red blood cell distribution width levels have poor prognoses." (PMID 38877408, 2024). "This study utilized Group-based Trajectory Modeling (GBTM) to investigate the patterns of serum albumin changes and their impact on sepsis outcomes." (PMID 39101009, 2024). "Experimental studies have described protective functions of albumin in animal models of sepsis through oncotic, antioxidant and anti-inflammatory mechanisms." (PMID 38326920, 2024). "The most prevalent variables used for ML-based sepsis mortality prediction included age, lactate, albumin level, use of a ventilator, temperature, blood urea nitrogen, serum creatinine, and bilirubin." (PMID 39767798, 2024).
Sepsis (continued). "In a meta-analysis, a comparison with crystalloid revealed a trend towards reduced 90-day mortality in severe sepsis patients who underwent resuscitation with albumin (OR: 0.88; 95% CI, 0.76 to 1.01; P = 0.08)." (PMID 39048942, 2024). "Lower serum albumin levels have been observed in patients with sepsis because of the modified distribution of albumin between the extravascular and intravascular compartments caused by increased microvascular permeability." (PMID 38877408, 2024). "Next, albumin has well characterized antioxidant functions which is relevant in the context of sepsis, where high oxidative state participates in endothelial NO synthase dysregulation, leading to impaired vascular tone." (PMID 38326920, 2024). "Against the background delineated above, the current investigation endeavors to assess the connection between serum albumin levels at admission and their implications for patient outcomes in sepsis within the ICU." (PMID 38826606, 2024). "Conversely, lower serum albumin levels were linked to higher SOFA scores, indicating more severe sepsis." (PMID 39539863, 2024). "The lactate-to-albumin ratio has a moderate predictive value for mortality in patients with sepsis or septic shock (AUC 0.74), with pooled sensitivity, specificity, and diagnostic odds ratios of 0.71, 0.68 and 5.23, respectively." (PMID 38898431, 2024). "The correlation between plasma albumin levels and such markers would provide an idea as to the relationship between inflammatory markers, plasma albumin, and mortality in sepsis." (PMID 39459557, 2024). "Many studies around the globe have endorsed this finding of the present study regarding the correlation between serum albumin level and the severity of sepsis." (PMID 39539863, 2024). "As albumin contributes to the increase in colloid osmotic pressure, several studies have confirmed its potential therapeutic use in diseases such as sepsis and other conditions." (PMID 38195421, 2024). "The figure sets the stage for future studies to explore the mechanistic pathways of albumin’s impact on sepsis-related complications, paving the way for more tailored and effective treatment strategies." (PMID 38139434, 2023). "Currently, both large and small molecules have been used for the treatment and prevention of sepsis, such as human serum albumin (HSA) and antibiotics." (PMID 37629199, 2023). "Certain factors have been identified as independent predictors of postoperative SIRS/sepsis, including a high preoperative heart rate, low albumin levels before surgery, and intensive care unit (ICU) admission after the operation." (PMID 37809261, 2023). "This review aims to emphasize personalized albumin therapy in sepsis and underscores the need for further research to define the role of albumin in sepsis pathophysiology and its potential benefits for specific patient groups." (PMID 38139434, 2023). "Although serum lactate and serum albumin have individual predictive values for mortality in sepsis and critically ill patients, the combined effect of the serum lactate/albumin (L/A) ratio is a better predictor." (PMID 37123772, 2023). "A recent study on sepsis treatment compared the use of crystalloids combined with albumin to crystalloids alone." (PMID 36909040, 2023). "Although some studies have shown that the ability of colloids to expand is lower in sepsis, the expanding ability of albumin is still higher than that of crystalloids under the same condition." (PMID 37089426, 2023). "The Albios study published in 2014 evaluated the effect of albumin in patients with sepsis and septic shock." (PMID 37218881, 2023). "The observed results open avenues for future investigations with larger sample sizes and more comprehensive patient representations, allowing for a deeper exploration of the role of albumin in sepsis management." (PMID 37628734, 2023).
Sepsis (continued). "Continuous administration of albumin (for 3 consecutive days or more) to adult patients with severely or critically ill COVID‐19, hypoproteinemia, septic shock, or sepsis can restore plasma albumin levels and improve prognosis." (PMID 38020714, 2023). "A focused literature search was conducted using PubMed and Embase, utilizing key terms such as ‘albumin’, ‘sepsis’, ‘cirrhosis’, and ‘liver disease’." (PMID 38139434, 2023). "Cholesterol, which maintains the normal activity of the cell membrane, is affected by albumin, and both are thought to exacerbate sepsis conditions." (PMID 36832250, 2023). "The delayed return of albumin-rich lymph likely causes the misallocation of albumin during inflammatory conditions, as the production rate of albumin remains normal during major abdominal surgery and sepsis." (PMID 37762871, 2023). "Unlike its established role in cirrhosis-related complications, the clinical benefits of albumin in sepsis are less definitive." (PMID 38139434, 2023). "It is well known that the development of ABE is determined by gestation, birth weight, associated morbidity like sepsis and gastrointestinal obstruction, peak of total serum bilirubin (TSB), age at peak TSB, serum albumin, and the presence of hemolysis." (PMID 35969370, 2023). "The serum albumin level has recently been identified as a prognostic factor in patients with sepsis in the ICU." (PMID 38137746, 2023). "This parallel underscores the potential for applying insights from albumin efficacy in cirrhosis to the management of sepsis." (PMID 38139434, 2023). "The team agreed on an action plan including a) educational workshops for albumin's rational use in sepsis and septic shock fluid resuscitation, b) justifying the volume of crystalloids administered prior to prescribing albumin." (PMID 36874589, 2023). "In these studies, u-Gc significantly correlated with u-albumin, similarly to our findings in sepsis." (PMID 37836706, 2023). "They found CRP/albumin to be statistically significant for exitus, infection, sepsis and liver failure." (PMID 38024343, 2023). "A prospective cohort study reported that increasing the amount of albumin improves the prognosis of patients with severe sepsis." (PMID 37046520, 2023). "Because vascular permeability increases in sepsis, large molecules such as albumin can leak into the interstitium." (PMID 37099566, 2023). "This narrative review clarifies the role of albumin in sepsis, based on its proven efficacy in cirrhosis-related complications." (PMID 38139434, 2023). "Prior studies have identified a relationship between sepsis status and prognosis and arterial blood lactate or serum albumin concentration." (PMID 37790597, 2023). "This approach to albumin use in sepsis management is posited as a way to potentially improve patient outcomes in this complex clinical scenario while being mindful of the lessons learned from its use in cirrhosis." (PMID 38139434, 2023). "Guidelines from SSC recommend the use of albumin in SS or sepsis patients treated with a large volume of crystalloids (weak recommendation, moderate quality of evidence)." (PMID 37089426, 2023). "Given the intricate interplay between liver function and the gut microbiota in both sepsis and cirrhosis, the theoretical rationale for closely comparing albumin therapy in these conditions is evident." (PMID 38139434, 2023). "The relationship between albumin administration, pneumonia, and pulmonary complications in the context of cirrhosis and sepsis is complex and requires further investigation." (PMID 38139434, 2023). "In contrast, the Surviving Sepsis Campaign 2021 suggested using albumin in patients who received large volumes of crystalloids over crystalloids alone for adults with sepsis or septic shock." (PMID 37277756, 2023). "Independent risk factors for sepsis in CRC patients with gastrointestinal perforation include anemia, intestinal obstruction, preoperative chemotherapy, acidosis, and low albumin levels." (PMID 37809261, 2023).
Sepsis (continued). "International guidelines for the management of sepsis and septic shock: Surviving Sepsis Campaign” graded recommendations for albumin administration in adults with sepsis or septic shock as weak." (PMID 37218881, 2023). "In sepsis, increased microvascular permeability in an inflammatory state alters the intra- and extravascular distribution of albumin, resulting in lower serum albumin concentrations in critically ill patients." (PMID 37340147, 2023). "Admission se-creatinine and u-ALB levels were higher (p < 0.05) in the sepsis-related AKI group than in the control group; moreover, they also tended to be higher (p < 0.05) in sepsis-related AKI patients when compared to septic patients." (PMID 37836706, 2023). "Full-text publications, paid and free, indexed in PubMed, Cochrane Library, and ScienceDirect were searched from inception to 2023, using the keywords "Sepsis”, “Crystalloids”, "Colloids" and “Albumin”." (PMID 37779759, 2023). "This narrative review critically examines the role of albumin in sepsis management and compares it to its well-established application in liver cirrhosis." (PMID 38139434, 2023). "The differential impact of albumin dosage in cirrhosis and sepsis treatment indicates the need for continued research to determine the optimal treatment protocols in sepsis." (PMID 38139434, 2023). "These trials, which included SAFE, ALBIOS, and EARSS, collectively indicated a trend towards reduced mortality in sepsis patients receiving albumin with relative risks closely aligning from 0.87–0.94." (PMID 38139434, 2023). "Limited knowledge is available on the functional properties of albumin in critically ill patients with sepsis or septic shock." (PMID 37628734, 2023). "The “Albumin Italian Outcome Sepsis” (ALBIOS) trial investigated 20% albumin with crystalloids versus crystalloids alone in patients with sepsis or septic shock, showing similar 90-day survival rates." (PMID 38139434, 2023). "According to the reviewed research articles, MIP-based biosensors can be applied for inflammation and sepsis biomarkers, such as human serum albumin, C-reactive protein, serum amyloid A, tumor necrosis factor-alpha (TNF-α), procalcitonin, IL-6, and IL-1β." (PMID 37366985, 2023). "In the context of sepsis, these inflammation-related ROS play a pivotal role in orchestrating alterations in the conformation and functionality of albumin, primarily through oxidation of the critical Cys34 residue within the albumin molecule." (PMID 37628734, 2023). "Our analysis also indicated that the lower the ALB level, the more patients with sepsis and the higher the inflammation indicators." (PMID 37946135, 2023). "The ALBIOS study was a trial to compare the safety and efficacy of albumin replacement in patients with sepsis." (PMID 37779759, 2023). "Plasmapheresis should be avoided in patients with hemodynamic instability, septicemia, or a history of prior anaphylaxis reaction to one of the components of plasmapheresis, such as albumin, FFP, or heparin." (PMID 38138254, 2023). "This study aimed to evaluate the clinical value of the procalcitonin-to-albumin ratio (PAR) in identifying sepsis in neonates with pneumonia." (PMID 36908271, 2023). "The major contraindications to Therapeutic Apheresis treatments are hemodynamic instability, sepsis, and a history of allergy to the substitution fluid (albumin or fresh frozen plasma)." (PMID 36983698, 2023). "Before prescribing albumin to patients with sepsis or septic shock, the criteria for proper use of human albumin are established as a crystalloid dose higher than 25ml/kg." (PMID 36874589, 2023). "The potential effectiveness of albumin in the low-volume resuscitation and deresuscitation phases of sepsis management was noted." (PMID 38139434, 2023). "The need for further research to delineate the role of albumin in sepsis pathophysiology is underscored." (PMID 38139434, 2023).
Sepsis (continued). "Albumin replacement was found to be safe and showed efficacy in reducing mortality in patients with sepsis and septic shock." (PMID 37779759, 2023). "ALB replacement in addition to crystalloids improves the haemodynamics of patients with severe sepsis during the first 7 days." (PMID 37626308, 2023). "A sepsis patient’s serum ALB can decrease due to various factors including hypermetabolic state, gastrointestinal dysfunction, capillary leakage." (PMID 37626308, 2023). "The result showed no statistical difference was observed between the two groups in age, gender, underlying diseases, origins of sepsis, needing mechanical ventilation, WBC count, CRP, and ALB levels (p > 0.05)." (PMID 38298508, 2023). "A multivariable model that included 6 variables: weight, SOFA score, white blood cell count, albumin, chronic heart failure, and sepsis." (PMID 37884898, 2023). "Practical recommendations for clinicians include personalized albumin therapy for sepsis tailored to individual patient needs based on clinical presentation and conditions." (PMID 38139434, 2023). "The “randomized-controlled trial comparing 20% ALbumin to Plasmalyte in patients with cirrhosis and Sepsis-induced hypotension” (ALPS) compared 20% albumin to balanced crystalloid in cirrhotic patients with sepsis-induced hypotension." (PMID 38139434, 2023). "In sepsis, the potential benefits of albumin include maintaining vascular integrity and modulating inflammation, yet its consistent clinical efficacy is not as definitive as that in cirrhosis." (PMID 38139434, 2023). "The diagnostic accuracy of the L/A ratio was excellent in predicting mortality and hospital stay (discharge) among sepsis subjects as compared to lactate and albumin alone." (PMID 37123772, 2023). "Current studies demonstrate a strong correlation between serum albumin and mortality and prognosis in conditions, such as sepsis, tumors, and kidney diseases." (PMID 37817258, 2023). "This study developed a novel nomogram for predicting risk of AKI in ICU patients with AP, comprising weight, SOFA score, sepsis, chronic heart failure, white blood cell count, albumin." (PMID 37884898, 2023). "Future research should aim to explore these complex relationships further, focusing on the optimal use of albumin in sepsis treatment." (PMID 38139434, 2023). "In conclusion, a higher lactic acid, sequential organ failure assessment score, eGFR, and a lower albumin level have prognostic value to predict mortality in patients with sepsis initiating CRRT." (PMID 36832265, 2023). "NICE recommends crystalloids as a first-line treatment for hypotension in sepsis, considering albumin as a second-line therapy in severe cases." (PMID 38139434, 2023). "Understanding the various roles of albumin is important, especially in the context of cirrhosis and sepsis." (PMID 38139434, 2023). "Future studies should evaluate the potential of HMG-CoA reductase inhibitors, albumin dialysis and other therapies to reduce immunosuppressive bile acids and their effects on sepsis outcome." (PMID 37759239, 2023). "Potential treatments that need to be considered while treating for sepsis to prevent ARDS are albumin infusion, bed elevation, and early antibiotics." (PMID 36909040, 2023). "Although there have been numerous studies investigating the relationship between ferritin and albumin and various diseases, the association between the ferritin-to-albumin ratio (FAR) and sepsis remains unexplored." (PMID 37817258, 2023). "Our results on changes in the molecular conformation of albumin provide further evidence for a relationship between liver function in the context of sepsis." (PMID 37628734, 2023). "It has been demonstrated that lactate/albumin (L/A) ratio is substantially relevant to the prognosis of sepsis, septic shock, and heart failure." (PMID 37730950, 2023).